NLRP3 (NLR family pyrin domain containing 3)
Diseases named in the same sentence as NLRP3 in open-access papers (continued):
Sharing a sentence is not in itself a finding about the gene and the disease.
Alzheimer disease (continued). "Additionally, NLRP3 deficiency led to a decrease in the amyloid-β levels and deposition suggesting an aggravating role of the NLRP3 inflammasome in the pathology of Alzheimer’s disease." (PMID 33534121, 2021). "Interestingly, the NLRP3-inflammasome has also been demonstrated to associate with other CNS inflammatory disorders, including Alzheimer’s disease (AD), which is an increased risk factor following TBI." (PMID 28124982, 2017). "However, excessive activation of the NLRP3 inflammasome also contributes to the progression of various inflammatory diseases, such as cryopyrin-associated periodic syndrome, arthritis, atherosclerosis, type 2 diabetes and Alzheimer’s disease." (PMID 38267403, 2024). "However, excessive activation of the NLRP3 inflammasome has been implicated in a wide variety of diseases, such as cryopyrin-associated periodic syndrome, arthritis, atherosclerosis, type 2 diabetes, Alzheimer’s disease, and cancer." (PMID 38267403, 2024). "Researchers have reported that NLRP3 inflammasome is associated with a range of aseptic inflammatory diseases such as diabetes, arteriosclerosis, systemic lupus erythematosus, rheumatoid arthritis, and central nervous diseases such as Alzheimer's disease (AD) and Parkinson's disease (PD)." (PMID 31681133, 2019). "In a mouse model of Alzheimer's disease, the oral NLRP3 inflammasome inhibitor, OLT1177, improved learning and memory deficits in the Morris water maze, restored LTP deficits in Schaffer collateral synapses, and reduced microglial reactivity." (PMID 41549052, 2026). "The NLRP3 inflammasome contributes to a wide range of conditions from infections to Alzheimer's disease." (PMID 42215451, 2026). "NOD-like receptor protein 3 (NLRP3) inflammasome-driven neuroinflammation contributes to Alzheimer's disease (AD) progression, yet effective strategies to target this pathway are limited." (PMID 42152587, 2026). "In Alzheimer’s disease, the accumulation of amyloid β plaques triggers the activation of the NLRP3 inflammasome, resulting in increased production of IL-1β, which subsequently recruits immune cells and exacerbates neuronal damage." (PMID 40075143, 2025). "Previous investigators revealed that NLRP3 inflammasome activation plays a critical role in Alzheimer's disease." (PMID 40357234, 2025). "SGD exerts neuroprotective and cognitive improvement effects by reducing NLRP1 and NLRP3 in Alzheimer’s disease cell and mouse models." (PMID 41190029, 2025). "In an Alzheimer’s disease mouse model, liraglutide suppresses microglial activation of the NLR family pyrin domain containing 3 (NLRP3) inflammasome, thereby reducing pro-inflammatory cytokine production and Aβ plaque burden." (PMID 41226780, 2025). "Recent investigations have also shown that TFE3 enhances autophagy, promoting the degradation of NLRP3 (NLR family pyrin domain containing 3), thereby inhibiting neuroinflammation in Alzheimer's disease models." (PMID 39759118, 2025). "The NLRP3 inflammasome plays a crucial role in various inflammation-related diseases, such as arthritis, Alzheimer's disease, and inflammatory bowel disease, while miR- 223 - 3p has been shown to inhibit its expression by targeting NLRP3 mRNA." (PMID 40360974, 2025). "Caspases play an intricate role in modulating the NLRP3 inflammasome and its consequent impact on Alzheimer’s disease (AD) pathology." (PMID 40427569, 2025). "In general, the development of an NLRP3 inflammasome is involved in neurodegenerative ailments such as Alzheimer's disease." (PMID 40231522, 2025). "The NLRP3 inflammasome has emerged as a crucial mediator of microglial-driven inflammation in Alzheimer's disease." (PMID 40046336, 2025). "The NLRP3-ASC inflammasome, a critical sensor of innate immunity, presents a promising therapeutic target for addressing key pathogenic processes in Alzheimer’s disease, including prion-like Tau pathology seeding, amyloid pathology, and neuroinflammation." (PMID 40538660, 2025).
Alzheimer disease (continued). "Our findings demonstrate that S-GLSP alleviates Alzheimer’s disease pathology by inhibiting NLRP3 inflammasome activation, promoting a shift in microglial polarization from the M1 to the M2 phenotype, and modulating the release of inflammatory cytokines." (PMID 41378217, 2025). "We have previously shown that nucleoside reverse transcriptase inhibitors (NRTI) reduce NLRP3 assembly in PBMCs of AD patients and enhance amyloid-β autophagy in macrophages, potentially offering therapeutic benefits for Alzheimer’s disease." (PMID 40867519, 2025). "NLRP3 is the most studied one and the one that seems to be most related to pyroptosis in Alzheimer’s disease, but other inflammasomes have also been reported to contribute to the disease, such as NLRP1." (PMID 40002308, 2025). "Accumulating evidence has identified NLRP3-mediated neuronal pyroptosis as a critical mechanism in neurodegenerative disorders such as Alzheimer’s disease." (PMID 41002402, 2025). "SAB has also been proposed as a promising candidate for treating Alzheimer’s diseases by regulating NLRP3 inflammasome activity and promoting microglial M2 polarization." (PMID 40722987, 2025). "MicroRNAs have been shown to suppress NLRP3 expression, leading to improved cognitive function in rodent models of Alzheimer’s disease." (PMID 40260242, 2025). "There is a good deal of evidence linking inflammasomes, including NLRP3, with the induction of neuroinflammation and promotion of neurodegeneration, encompassing disorders such as Alzheimer’s disease, Parkinson’s disease, and amyotrophic lateral sclerosis." (PMID 39791736, 2025). "The NLRP3 inflammasome plays a pivotal role in Alzheimer’s disease by regulating neuroinflammatory responses." (PMID 41378217, 2025). "In an Alzheimer’s disease model, NLRP3-driven pyroptosis contributed significantly to disease progression, and dapansutrile ameliorated pathological changes via this pathway." (PMID 41415576, 2025). "These nanovectors enhance the efficacy of glibenclamide by promoting autophagy and reducing NLRP3 activation, illustrating the potential of nanotechnology in treating complex neurodegenerative disorders like Alzheimer’s disease." (PMID 40427569, 2025). "This intense inflammatory mechanism driven by NLRP3 activation is closely related to the neurodegeneration observed in Alzheimer's disease." (PMID 40231522, 2025). "Taken together, the results of the present study demonstrate that the ABCA7 transporter plays a key role in modulating both β-amyloidosis and inflammation induced by NLRP3 inflammasome in the APPPS1 mouse model of Alzheimer’s disease." (PMID 39871385, 2025). "The therapeutic potential of NLRP3 inflammasome inhibition by dapansutrile was demonstrated in a model of Alzheimer’s disease in mice." (PMID 41415576, 2025). "The NLRP3 inflammasome plays a pivotal role in the pathogenesis of Alzheimer’s disease by driving neuroinflammation, Aβ accumulation, tau pathology, and neuronal damage." (PMID 40260242, 2025). "Herein, we report the therapeutic benefit of NLRP3 inflammasome inhibition in Alzheimer’s disease (AD), using a novel and selective brain-penetrant small molecule NLRP3 inhibitor, VEN-02XX, which we profiled in the 5XFAD/Rubicon KO AD model." (PMID 40343261, 2025). "These keywords indicate that the NLRP3 inflammasome is the most studied neuroinflammatory component closely related to Alzheimer’s disease (AD) pathogenesis." (PMID 40538660, 2025). "Previous research has demonstrated that NLRP3 plays a significant role in various diseases, including inflammatory bowel diseases, kidney disorders, liver diseases, Parkinson’s disease, and Alzheimer’s disease." (PMID 39742284, 2024). "In Alzheimer’s disease, microglial activation via the NLRP3 inflammasome and complement system dysregulation highlight the dual role of microglia in both defense and damage, where failure to resolve inflammation accelerates synaptic loss and neuronal injury." (PMID 39769374, 2024).
Alzheimer disease (continued). "In Alzheimer’s disease, the NLRP3 inflammasome assembles inside of microglia upon activation, leading to increased cleavage and activity of caspase-1, resulting in neurodegeneration and cognitive decline." (PMID 38645501, 2024). "Inflammasomes, which make up a collection of polyprotein complexes present within microglial cells, have been shown to play a significant role in the pathology of Alzheimer’s disease, with a specific emphasis on the NLRP3 inflammasome." (PMID 39596378, 2024). "These chronic neuro-inflammatory responses are thought to increase hyperphosphorylation of tau protein and amyloid-β, two precursors that worsen Alzheimer’s disease through NLRP3 inflammasome activation." (PMID 38644450, 2024). "The technique was also applied to target components of the NLRP3 inflammasome, which has been shown to significantly decrease neuroinflammation in mice with Alzheimer’s disease." (PMID 39852123, 2024). "An increasing body of research suggests that promoting microglial autophagy hinders the neuroinflammation initiated though the NLRP3 inflammasome activation in Alzheimer’s disease (AD)." (PMID 38630150, 2024). "In summary, the activation of microglial NLRP3 inflammasome by amyloid contributes to the release of pro-inflammatory cytokines, fostering the development of Alzheimer's disease pathology." (PMID 38317229, 2024). "By reducing cytokine production as well as decreasing microglial activation, siRNAs that target TNF-α or NLRP3 inflammasome components, for example, have shown significant effectiveness in preclinical models of Parkinson’s and Alzheimer’s diseases." (PMID 39852123, 2024). "In Alzheimer’s disease, for instance, amyloid beta plaques activate the NLRP3 inflammasome, contributing to chronic inflammation and neuronal damage." (PMID 39852123, 2024). "The findings of this study provide compelling evidence that DAG-MAG-βHB impairs the assembly of the NLRP3 inflammasome, a key driver of neuroinflammation in Alzheimer’s disease." (PMID 39796582, 2024). "Alzheimer's disease, TBI, and other neurodegenerative illnesses have been associated with inflammatory processes, namely those related to the NLRP3 inflammasome." (PMID 39286668, 2024). "Luteolin has previously been reported to inhibit ER stress-induced neuroinflammation in Alzheimer’s disease mouse model and to suppress lipotoxicity-induced NLRP3 inflammasome activation in macrophages by reducing ER stress." (PMID 39459041, 2024). "It proved that STING, NLRP3 or IL‐1β gene had important roles in the progression of Alzheimer's disease." (PMID 37528567, 2024). "Recently, oligodendrocytes were also shown to induce NLRP3 activation upon glycolytic stress in Alzheimer’s disease (AD)." (PMID 38722788, 2024). "In neurodegenerative diseases such as Alzheimer’s disease, Parkinson’s disease, amyotrophic lateral sclerosis, and MS, dysregulation of this complex can trigger and sustain NLRP3 inflammasome activation and thereby drive CNS neuropathology." (PMID 37702910, 2024). "A defective NLRP3 inflammasome was found to result in reduced Aβ deposition in the APP/PS1 model of Alzheimer’s disease." (PMID 37940779, 2024). "The NLRP3 inflammasome is also a key element in Alzheimer’s disease (AD); its activation induces increased synthesis of pro-IL-1β and pro-IL-18 and activates caspase-1." (PMID 38928621, 2024). "Activation of the NLRP3 inflammasome is involved in the pathogenesis of many neurodegenerative disorders, such as PD, Huntington’s disease, Alzheimer’s disease, amyotrophic lateral sclerosis, multiple sclerosis, and prion diseases." (PMID 36757612, 2023). "For this reason, small molecules that can modulate autophagy and the NLRP3 inflammasome have been proposed as treatments for neurodegenerative diseases such as Alzheimer’s disease." (PMID 37124206, 2023).
Alzheimer disease (continued). "Studies have shown that activation of NLRP3 inflammasome contributed to tau pathology and promoted Alzheimer’s disease progression, and inhibition of NLRP3 inflammasome with MCC950 improved cognitive decline after stroke in diabetic animals." (PMID 37312196, 2023). "Emerging research has unveiled advantageous effects of flavonols on various neurodegenerative diseases, including Alzheimer’s disease, Parkinson’s disease, and stroke, largely attributed to their modulation of NK-κB and NLRP3 inflammasome pathways." (PMID 37836410, 2023). "The fenamate nonsteroidal anti-inflammatory drugs were shown to inhibit the NLRP3 inflammasome and thereby protected against Alzheimer’s disease in rodent models." (PMID 36669831, 2023). "Activation of the NLRP3 inflammasome is closely related to the occurrence of many diseases, such as Alzheimer's disease." (PMID 36378463, 2023). "The interrelation of the NLRP3 inflammasome and other cerebrovascular and/or neurodegenerative diseases such as Alzheimer’s disease (AD) has also been investigated." (PMID 36676165, 2023). "PM2.5 exposure worsens oligomeric amyloid beta-induced neuronal damage and enhances NLRP3 inflammasome activation in an Alzheimer’s disease in vitro model." (PMID 38173557, 2023). "This drug inhibits Alzheimer’s disease-related cognitive impairment in a rodent model, which provides an option for the treatment of NLRP3-related inflammatory diseases." (PMID 36378463, 2023). "In relation to NLRP3 expression, miR-223-3p—which downregulates NLRP3 activity—shows differential expression in the serum of patients with Alzheimer’s disease and mild cognitive impairment compared to those with PD." (PMID 37375830, 2023). "In Alzheimer’s disease, the NLRP3 inflammasome was postulated to interconnect systemic inflammation with neuro-inflammation by impairing the removal of amyloid-beta via the microglia." (PMID 37242177, 2023). "This study aimed to elucidate the role of NLRP3 inflammasome in cognitive decline in depression and explore the common neuro-immunological mechanisms of depression and Alzheimer’s disease (AD)." (PMID 37165444, 2023). "It has been shown that NLRP3 is elevated in patients with Alzheimer’s disease, viral encephalitis, MS, traumatic brain injury, stroke, Parkinson’s disease, epilepsy, and other diseases." (PMID 36389787, 2022). "Aβ plaques not only induce oxidative stress and damage neurons, but also activate NLRP3 inflammasomes further releasing IL-1β to trigger neuroinflammation in patients with Alzheimer’s disease." (PMID 36009120, 2022). "It has been demonstrated that the NLRP3 inflammasome is crucial for COVID-19 and the development of Alzheimer’s disease." (PMID 35669789, 2022). "This review focuses on the potential applications of CA and CS for Alzheimer’s disease (AD), Parkinson’s disease (PD), and coronavirus disease 2019 (COVID-19), in part via inhibition of the NLRP3 inflammasome." (PMID 35052628, 2022). "We suggest that CS ameliorates COVID-19 and Alzheimer’s disease, at least in part, by inhibiting the NLRP3 inflammasome." (PMID 35669789, 2022). "Osthole (OST) reduced hippocampal Aβ deposition and improved cognitive dysfunctions in the rat model of Alzheimer’s disease by NLRP3 inflammasome suppression via a PI3K/Akt/GSK-3β signaling pathway." (PMID 36009120, 2022). "The aberrant activation of NLRP3 inflammasome is demonstrated to be involved in traumatic brain injury, neuropathic pain, Alzheimer’s disease, etc., indicating that NLRP3 inflammasome is crucial for the process of neuroinflammation." (PMID 35387668, 2022). "Studies have demonstrated important roles of the NLRP3 inflammasome in aging and age-related diseases, such as atherosclerosis metabolic syndrome, type 2 diabetes, and Alzheimer’s disease." (PMID 35838044, 2022). "NLRP3 inflammasome activation modulates neuroinflammation, tissue damage, and cognitive impairment commonly found in the mouse model of Alzheimer’s disease." (PMID 36009120, 2022).
Alzheimer disease (continued). "Intestinal bacteria in the patients with Alzheimer’s disease mediate neuroinflammation via NLRP3 inflammasome activation." (PMID 36009120, 2022). "In the central nervous system, the significant elevation of IL-1β in the cerebrospinal fluid of brain injury, Alzheimer’s disease, and multiple sclerosis depends on the activation of NLRP3 within microglia." (PMID 35754513, 2022). "Transplantation of the gut microbiota from Alzheimer’s disease patients into APP/PS1 double transgenic mice as a model of the disease increased expression of NLRP3 and led to more severe cognitive impairment." (PMID 35631301, 2022). "The keywords used as search terms for our literature review were ‘Rosmarinus officinalis’, ‘rosemary’, ‘carnosic acid’, ‘carnosol’, ‘NLRP3′, ‘Alzheimer’s disease’, ‘Parkinson’s disease’, ‘COVID’, and ‘NRF2′." (PMID 35052628, 2022). "MCC950 is a highly selective and potent small-molecule inhibitor of NLRP3 that has been used for the treatment of several diseases such as Alzheimer’s disease." (PMID 35219323, 2022). "Bifunctional molecule BPBA inhibits Aβ aggregation and NLRP3 inflammasome activation, thereby decreasing ROS and IL-1β in vitro and vivo; it synergistically prevents Alzheimer's disease via alleviating Aβ neurotoxicity and reducing neuroinflammation." (PMID 35382471, 2022). "ROS also evokes Alzheimer's disease through active NLRP3, which promotes IL-1β-mediated inflammation." (PMID 35030992, 2022). "Mechanism of electroacupuncture targeting NLRP3 inflammasome in the treatment of stroke, Alzheimer’s disease and spinal cord injury." (PMID 36337711, 2022). "An increasing body of evidence suggests that NLRP3 participates in the formation of inflammasomes in several neurodegenerative diseases, such as Alzheimer’s disease and Parkinson’s disease." (PMID 35431795, 2022). "In this respect, cathepsins have been proved to activate the NLRP3 inflammasome in Alzheimer’s disease microglia." (PMID 35216110, 2022). "NLRP3 inflammasome activation has been known to be involved in the etiology and progression of Alzheimer’s disease (AD)." (PMID 36422510, 2022). "Aberrant activation of the NLRP3 inflammasome is also involved in the development of several neurodegenerative disorders, such as PD, Alzheimer’s disease (AD), and multiple sclerosis." (PMID 35721113, 2022). "NLRP3 inflammasome-mediated neuroinflammation plays a critical role in the pathogenesis and development of Alzheimer’s disease (AD)." (PMID 35918778, 2022). "This article, along with the second-, fifth-, sixth-, and seventh-ranked literature, discussed the specific mechanisms of NLRP3 inflammasome signaling axis in the pathogenesis of Alzheimer’s disease (AD) and other neurodegenerative diseases." (PMID 36160384, 2022). "The possibility of drug repurposing has also been identified for targeting NLRP3 in Alzheimer's disease." (PMID 33597269, 2021). "We also measured insulin in the brain amygdala to analyze how its expression level changes when modeling Alzheimer’s disease in NLRP3 knockout mice." (PMID 34769018, 2021). "In neurological diseases, it has been found that NLRP3 inflammasome is involved in the neuroinflammatory response of Alzheimer’s Disease (AD), ischemic stroke, multiple sclerosis and other diseases, and is closely linked to the development of these diseases." (PMID 34526897, 2021). "Dysfunctional autophagy promotes microglial activation through regulating the production of IL1β and IL18 via NLRP3 degradation, and it contributes to neuroinflammation in Alzheimer’s disease (AD)." (PMID 33402188, 2021). "Deficiency of NLRP3 and caspase-1 resulted in protection from cognitive impairment and memory loss in an APP/PS1 mouse model of Alzheimer's disease." (PMID 33534121, 2021). "Two studies showed that chronic HIIT markedly inhibited the NLRP3 inflammasome overactivation in hippocampus of mice with Alzheimer’s disease and stroke-induced depression." (PMID 34639204, 2021).